TLR2 (toll like receptor 2)
Diseases named in the same sentence as TLR2 in open-access papers (continued):
Sharing a sentence is not in itself a finding about the gene and the disease.
autoimmune disease (45 papers, 2011 to 2025). A disorder resulting from loss of function or tissue destruction of an organ or multiple organs, arising from humoral or cellular immune responses of the individual to their own tissue constituents. "L. plantarum ATCC14917 PG, L. casei, and L. johnsonii JCM 2012 have been used to suppress IL-12 production while interacting with toll-like receptor 2 (TLR2), which further causes autoimmune diseases and inflammatory bowel disorders." (PMID 35781838, 2022). "TLR2 is associated with the pathogenesis of several autoimmune diseases." (PMID 39897071, 2024). "Thus, blockade of CLEC5A and TLR2 using a bi-specific anti-CLEC5A/TLR2 mAb has the potential to reduce the risk of autoimmunity post-DV infection, and have therapeutic effects in autoimmune diseases by limiting excessive NET formation and persistent inflammasome activation." (PMID 31867016, 2019). "TLR2/4 expression was increased in peripheral blood mononuclear cells and monocytes from patients with a variety of autoimmune diseases, including type 1 diabetes, RA and SLE." (PMID 36778150, 2023). "In other autoimmune diseases, such as spondyloarthropathy and Behcet’s disease, TLR2 expression is downregulated after infliximab therapy, supporting the role of TLR2 in the response to the anti-TNFα therapy." (PMID 35517818, 2022). "Recent studies have revealed Toll-like receptor 2 to be significant in the pathogenesis of autoimmune diseases." (PMID 34566978, 2021). "TLR2 affects T cell polarization and differentiation, and plays a crucial role in development of experimental autoimmune disease." (PMID 34394755, 2021). "Recent studies in autoimmune diseases suggest that increased expression of TLR2 in CD4+ T cells enhances immune reactivity and promotes IL-17 expression through upregulating H3K4 while downregulating H3K9 tri-methylation level in SLE." (PMID 34367251, 2021). "Patients with systemic lupus erythematosus, an autoimmune disease associated with both PGN and NPGN, had increased expression of TLR2 mRNA in the peripheral blood mononuclear cells compared to healthy controls." (PMID 32079183, 2020). "Recent studies on other autoimmune diseases, such systemic lupus erythematosus, have shown that microbial curli fibers can lead to the activation of TLR2 and TLR9 on DCs, thus stimulating immune responses, including increased type I IFN production." (PMID 31273267, 2019). "Amyloid-DNA composites are known to intensively stimulate TLR2 and TLR9, inducing immunogenic reactions, and they have been associated with the triggering of other autoimmune disorders, including systemic lupus erythematosus." (PMID 31273267, 2019). "It has been shown that TLR2 signaling in CD4+ T lymphocytes promotes Th17 responses in an autoimmune disease mouse model." (PMID 29218046, 2017). "We have demonstrated that PDHCs can promote autoimmune disease in mice and that this process is dependent on expression of TLR2." (PMID 21347306, 2011). "Correale and Farez evidenced that a soluble egg Ag (SEA) obtained from Schistosoma mansoni exerts potent regulatory effects on both DCs and B cells through TLR2 regulation in patients with the autoimmune disease, multiple sclerosis." (PMID 21943110, 2011). "TLR2/TLR4 have emerged as targets for treating a wide array of autoimmune disorders." (PMID 36969199, 2023). "As the same group also found lower L654 concentrations in serum of patients with multiple sclerosis, it was suggested that steady-state exposure to TLR2-tolerizing bacterial products originating from the gut microbiome helps to protect against autoimmune diseases." (PMID 35278409, 2022). "Another study showed that TRIM58 might protect against the transduction of intestinal mucosal inflammation by inhibiting abnormal TLR2 signaling and serve as a potential therapeutic target in autoimmune diseases, such as ulcerative colitis." (PMID 34435051, 2021).
autoimmune disease (continued). "It would be interesting to test whether EV-CLEC5A/TLR2 interactions contribute to the pathogenesis of aseptic inflammation and autoimmune diseases in the future." (PMID 31867016, 2019). "The PBD carries a significant segment, the PBM, that could serve as a decoy to prevent or dissociate TIRAP from the membrane in order to control dysregulated and overexpressed TLR2/TLR4/TLR7/TLR9-dependent autoimmune diseases." (PMID 29434596, 2018). "Effects of ligands of TLR2 or TLR4 on different cells in autoimmune diseases." (PMID 27199979, 2016). "Moreover, we determined that Breg activation is induced by YZP through the TLR2/4-mediated signaling pathway and evaluated the immunotherapeutic potential of this protein against autoimmune diseases." (PMID 24019869, 2013). "Furthermore, Tlr2 activation in immune cells during chronic inflammation can contribute to the pathogenesis of chronic diseases, such as autoimmune diseases." (PMID 35350715, 2022). "That TLR2 signaling could be able to modulate both of these pathways, at least in human monocytes, might then present a possible target for clinical intervention in both infectious and autoimmune diseases." (PMID 29896111, 2018). "TLR2, TLR4, TLR7, and TLR9 recognize PAMPs from infectious agents and DAMPs from tissue damage, contributing uniquely to the pathogenesis of specific autoimmune diseases." (PMID 38732254, 2024). "For example, in macrophages, TIM-3 is responsible for regulating the response to toll-like receptor 2 (TLR2) and toll-like receptor 4 (TLR4) stimulation, thus inhibiting the release of proinflammatory cytokines in autoimmune diseases." (PMID 37345111, 2023). "The binding of extracellular HMGB1 to Toll-like receptors (TLRs), such as TLR2 and TLR4 transforms HMGB1 into a pro-inflammatory cytokine, contributing to the occurrence and development of autoimmune diseases." (PMID 37667233, 2023). "Our findings that TLR2 and TLR4 expression and induction are altered in children with DS suggest a possible role for these pathogen receptors in the development of autoimmune diseases in this group." (PMID 31611734, 2019). "As a contributor to TLR2/TLR4 pathway, it has been attributed a pivotal function in the pathogenesis of autoimmune diseases." (PMID 26442097, 2015). "Caution is needed when selecting appropriate TLR2 adjuvants for Treg induction, because some ligands for TLR2/TLR1 signaling such as Pam3Cys have been shown to skew Treg toward a Th17 phenotype and might therefore increase the risk of developing autoimmune disease." (PMID 23970886, 2013). "TLRs, such as TLR2, TLR4, TLR7, and TLR9, are involved in this process, and their dysfunction or overexpression in immune cells plays a pivotal role in the pathogenesis of autoimmune diseases." (PMID 38732254, 2024). "For example, TLR2, TLR3, TLR4 and NOD1 are activated in in both human patients and in animal models of Sjogren’s syndrome and autoimmune disease against cells producing tears, saliva and mucus TLR7 and TLR9 are also implicated in the animal model though less certainly in human patients." (PMID 32629865, 2020). "This confirms the thesis that TLR-2 and TLR-4 may be involved in the development of autoimmune diseases." (PMID 31554206, 2019). "The present study extends our understanding of TIRAP’s membrane association, which could be helpful in designing peptide decoys to block TLR2-, TLR4-, TLR7-, and TLR9-mediated autoimmune diseases." (PMID 29434596, 2018). "CAT predicts that the original mice will not experience either autoimmune disease or chronic inflammation whereas the third mouse will develop experimental autoimmune myocarditis and develop chronic inflammation driven specifically by TLR2, 4 and 7 and NOD2." (PMID 32629865, 2020).
autoimmune disease (continued). "High levels of TLR2 and TLR4 expression on myeloid DCs and TLRs TLR7 and TLR9 present in pDCs may have specific functions in autoimmune disease in which molecular mimicry or autoantibodies to essential nucleic acids are a potential underlying mechanism for autoimmune disease onset." (PMID 28396662, 2017).
malaria (43 papers, 2008 to 2025). Malaria is a serious and sometimes fatal disease caused by a parasite that commonly infects a certain type of mosquito which feeds on humans. "In malaria naïve donors, Δ22 heterozygosity was associated with reduced pam3cys induced TLR2 stimulation in human monocyte derived macrophages." (PMID 22336003, 2012). "Malaria naïve North American volunteers were recruited and genotyped for TLR2 Δ22 and GTn polymorphisms." (PMID 22336003, 2012). "A total of 65 children with cerebral malaria and 52 children with uncomplicated malaria were genotyped for TLR2 insertion-deletion polymorphisms." (PMID 22336003, 2012). "This molecule is a downstream adaptor in the TLR2 signalling pathway, and this polymorphism is associated with protection from malaria and reduced signalling in vitro." (PMID 22336003, 2012). "This study is the first to describe the TLR2 5' untranslated polymorphisms in Kenyans and Papua New Guineans from malaria endemic areas." (PMID 19317913, 2009). "Further, due to limited cell numbers in malaria naive donors, we were also unable to investigate the specific innate cell pathways linked to differences seen following parasite simulation (for example, TLR2 or TLR4 pathways)." (PMID 41027884, 2025). "This is the first study to show an association between severe malaria and a TLR2 polymorphism." (PMID 22336003, 2012). "Known PAMPs in malaria include Plasmodium glycosylphosphatidylinositols (GPIs) that bind avidly to TLR2 and less stringently to TLR4." (PMID 39452740, 2024). "Here, we expanded those results by linking suppression of HSP70 with TLR2 and TLR4, HSP60, and associated signaling cascades in malaria-infected children with severe anemia." (PMID 39452740, 2024). "An overlapping set of genes, HP, ICAM1, IFNG, TLR2, and TLR4 were found to contain SNPs statistically significantly associated with malaria in both maternal and child analyses." (PMID 37287037, 2023). "Immune-related genes TLR2 in Malaria and Legionellosis and IL-18 and IL18R1 in the TNF signaling pathway were upregulated in the LG compared to in the BG (p < 0.05)." (PMID 35268235, 2022). "TLR2 in Malaria and Legionellosis and IL-18 and IL18R1 in the TNF signaling pathway were upregulated in the LG compared to in the BG (p < 0.05)." (PMID 35268235, 2022). "These recombinant CSPs lack the native parasite GPI anchor which is a known Toll-like receptor (TLR)-2/4 activating pathogen-associated molecular pattern (PAMP) in protozoa and plays a role in blood stage malaria." (PMID 32898164, 2020). "DNA and RNA play prominent roles in mouse malaria immunity and pathogenesis; under certain conditions TLR2 and TLR4 also play important roles." (PMID 30619355, 2018). "Taken together, MRP14 can be involved in the pathology of hepatic injury during malaria through activation of TLR2 and TLR4 signaling." (PMID 29902248, 2018). "As such, studies in various mouse models have demonstrated that TLR9, TLR7, TLR4, and TLR2 play important roles in malaria immunity and cerebral, placental and other severe malaria pathology." (PMID 30619355, 2018). "Differentially expressed probes form these canonical pathways that were previously shown to play a role in severe malaria pathogenesis were TLR2, TLR4, TLR8, HSPA6, CR1, C1qA, C1qB, C1qC, FOS, and GZMB." (PMID 26961973, 2016). "TLR probes showed a higher expression in severe malaria cases during acute illness (2.07-fold for TLR2, 2.19-fold for TLR8, 2.27 and 2.46-fold for TLR4 probes)." (PMID 26961973, 2016). "The leishmaniasis pathway had three probes in common with malaria (TLR2, TLR4, CR1), while Staphylococcus aureus infection had one (CR1)." (PMID 26961973, 2016). "The TLR probes showed a higher expression in severe malaria cases during acute illness (2.07-fold for TLR2, 2.19-fold for TLR8, 2.27 and 2.46-fold for the TLR4 probes)." (PMID 26961973, 2016).
malaria (continued). "Patients with severe and mild malaria also showed increased surface expression of TLR2 and TLR4 on CD14+ monocytes and cDCs and decreased intracellular expression of TLR9 on pDCs." (PMID 27716849, 2016). "In human malaria with P. falciparum, the TLR2/1 and TLR2/6 complexes recognize specific components of the glycosylphosphatidylinositols (GPIs), that are regarded as major factors contributing to malaria pathogenesis." (PMID 25408684, 2014). "TLR2 Δ22 heterozygosity was significantly more common in the uncomplicated malaria group (p = 0.005), indicating that the odds of cerebral malaria are 66% (odds ratio 0.34, 95% CI 0.16-0.73) lower in heterozygotes compared to either homozygote." (PMID 22336003, 2012). "The expression of TLR2 was lower on both monocytes (8 out of 11 subjects) and neutrophils (10 out of 11 subjects) from malaria patients, whereas expression of TLR4 was only affected on neutrophils (8 out of 12) from infected individuals." (PMID 22745844, 2012). "TLR2, TLR4, TLR9, and downstream signaling pathways of these proteins have recently been implicated in human malaria pathogenesis." (PMID 19317913, 2009). "Malaria-derived glycosylphosphatidylinositol (GPI) has been identified as a potential malaria "toxin" by activating TLR2 signaling." (PMID 19317913, 2009). "This study focused on TLR2, TLR4, TLR9 and MAL because these genes have been implicated in human malaria pathogenesis." (PMID 19317913, 2009). "The list of TLR ligands now includes malaria-derived molecules: Pf toxin, glycosylphosphatidylinisitol is recognized by TLR2 and TLR4, whereas parasite DNA complexed with haemozoin is a TLR9 ligand." (PMID 19691558, 2009). "Recently, a polymorphism in the TLR4 gene has been implicated in protection against malaria, while a variant of the TLR2-4 adapter Mal/TIRAP can provide protection against invasive pneumococcal infection, malaria, and TB." (PMID 18575596, 2008). "Additionally, malaria exposure trains the immune system to hyper-respond to the stimulation of TLR2, potentially increasing anti-CSP antibody levels in higher transmission areas." (PMID 37872492, 2023). "Previous work from our lab revealed that an initial exposure to P. falciparum–infected RBCs (iRBCs) or the natural malaria crystal hemozoin (Hz) induced human adherent PBMCs to hyperrespond to subsequent ligation of TLR2, even if the second exposure was several days after the first." (PMID 35642634, 2022). "While the involvement of TLR9, TLR4, and TLR2 in malaria immunity/pathology is evident from studies in both mouse malaria models and in humans, thus far none of the studies in endemic areas have revealed the association of TLR7 with human malaria immunity/pathology." (PMID 30619355, 2018). "In addition, the malaria parasites in TLR2−/− mice grew rapidly, and over 60% of mice died by day 12, while all the malaria parasites were cleared from the WT mice." (PMID 26667391, 2015). "The signal transduction pathway involved in systemic production of proinflammatory cytokines in case of malaria is initiated following the activation of the Toll like receptor 2 (TLR2) and TLR4 when they recognize glycosylphosphatidylinositols (GPIs) anchored on plasmodium membrane proteins." (PMID 22479409, 2012). "Human monocytes and murine macrophages treated with PPARγ agonists generate significantly less TNF in response to malaria-related inflammatory stimuli including parasite lysates and P. falciparum glycosylphosphatidyl inositol (GPI), a malaria toxin that interacts with TLR2." (PMID 21772838, 2012). "The data suggest that history of malaria exposure of the two Kenyan populations has not been involved in selection of TLR2, 4, and 9 or MAL polymorphisms." (PMID 19317913, 2009).
malaria (continued). "Befitting any general immune response mechanism, various cytokines may potentially modulate ICAM1 expression, of which we have found evidence for statistical association of IL1, IL4 (and its receptor, IL4R), IL6, IL13, TLR2, TLR4, and IFNG (and its receptor, IFNGR1) polymorphisms with malaria." (PMID 37287037, 2023). "Thus, malaria parasite GPI is mainly a TLR2-activating PAMP." (PMID 30619355, 2018). "Therefore, we then investigated whether proinflammatory cytokines in the liver were also responsible for the inhibitory role of TLR2 activity on malaria liver-stage development." (PMID 26667391, 2015). "Therefore, our data strongly support that TLR2 signaling could significantly inhibit the development of the malaria pre-erythrocytic stage." (PMID 26667391, 2015). "In malaria blood-stage infection, parasite DNA, RNA and GPI anchors interact with TLR9, TLR7 and TLR2, respectively." (PMID 41398915, 2025). "Within the malaria pathway, miR-146a suppresses the CD40L, CXCL8, IFNγ, TLR2, TLR4, and ITGβ2 genes." (PMID 29747626, 2018). "Even though the GPI-induced immune response is widely described to be mediated by pattern recognition receptors such as TLR2 and TLR4, previous studies have revealed that these two receptors are dispensable for the development of severe malaria pathology." (PMID 28560184, 2017). "Most results normalized in convalescence with the notable exception of pro‐inflammatory cytokine‐producing cells in SMA, and TLR‐2 and TLR‐4 expression during convalescence from all forms of malaria." (PMID 27027867, 2016). "Both toll-like receptors two and four (TLR2, TLR4), part of the KEGG malaria pathway, had higher expression in the severe cases compared to the uncomplicated malaria group (2.07-fold higher for TLR2, 2.27- and 2.46-fold higher for the TLR4 probes)." (PMID 26961973, 2016). "In convalescence, the expression of TLR‐2 and TLR‐4 was lower in all three clinical forms of malaria compared to levels observed in acute disease, but this difference was only significant in the UM group." (PMID 27027867, 2016). "We conducted this study to explore expression of CD11a, CD11b, CD11c, CD18, HLA‐DR, CD86, TLR‐2 and TLR‐4 and production of TNF‐α and IL‐6 by monocytes in Malawian children presenting with different clinical forms of malaria." (PMID 27027867, 2016). "CD36 and TLR2 collaboration leads to a pro-inflammatory response via ERK, p38, MAPK, JNK and NF-kB signaling following interaction with malaria-GPI anchors." (PMID 26385579, 2015). "Other differentially expressed PRRs such as TLR2 and TRL4 were upregulated after malaria relative to baseline, suggesting that the regulation of P. falciparum-inducible inflammation does not occur at the level of TLR expression." (PMID 24743880, 2014). "In malaria, P. falciparum releases Pf-GPI during schizogony, a lipid that activates TLR2/4 and contributes to inflammation and cytokinemia in malaria." (PMID 24586264, 2014). "Others have demonstrated the up-regulation of hepcidin in human and murine malaria, BMP- and IL-6-dependent in the latter, and a TLR2-dependent, IL-6-independent increase in Borrelia infection of mice." (PMID 22675442, 2012). "The adaptor protein tirap S180L SNP (rs8177374) has been reported to diminish TLR-2 and TLR-4 signaling and heterozygosis for this SNP has been claimed to confer protection against mild and severe malaria to an extent comparable to HbAs." (PMID 21457584, 2011). "Recent studies have shown that malaria GPI and hemozoin are ligands for TLR2 and TLR9, respectively." (PMID 19710907, 2009). "TLR1, TLR2, TLR4, TLR6, TLR7 and TLR9 have been reported to recognize malaria ligands." (PMID 33344264, 2020). "First line of defense for pathogen recognition arisen with toll-like receptors TLR2, TLR4 and TLR5 in different infectious diseases such as malaria (adj pval 0.014), amoebiasis (adj pval 0.027) and legionellosis (adj pval 0.039) according to GEA over KEGG database." (PMID 29028836, 2017).